NKTR (natural killer cell triggering receptor)
Diseases named in the same sentence as NKTR in open-access papers (continued):
Sharing a sentence is not in itself a finding about the gene and the disease.
tumor (continued). "Thus, it is proposed that BXCL701 stimulated macrophages rapidly prime the tumor microenvironment for other immune effector cells, those of which are similarly primed by a combination of checkpoint inhibition and NKTR- 214 stimulation." (PMID 30400835, 2018). "NKTR-262 and NKTR-214 combination treatment led to durable immune memory and resistance to secondary tumor challenge in multiple models correlating with spontaneous cytotoxic T cell response in secondary tumor lesions." (PMID 30400835, 2018). "NKTR-214 may sustain, expand, and drive the systemic anti-tumor response initiated by RT leading to tumor clearance and tumor specific immunologic memory." (PMID 30400822, 2018). "NKTR-214 has shown promising clinical results by enhancing systemic anti-tumor responses." (PMID 30400822, 2018). "Although speculative, it is conceivable that the residual IL2Rαβγ binding allowed by NKTR-214 activates protective Tregs in the peripheral blood where the CD8/Treg ratio is ~40-fold lower than that observed in the tumor." (PMID 28678791, 2017). "Importantly, a marked increase in the ratio of CD8/Tregs in the tumor was obtained after one single dose of NKTR-214 (>400) compared to ~18 for five daily doses of aldesleukin." (PMID 28678791, 2017). "Given the requirement of the IL2 pathway for T cell activation and proliferation, NKTR-214 may serve as a backbone therapy that enhances multiple anti-tumor modalities." (PMID 28678791, 2017). "Consequently, the conjugated-IL2 species occupy the IL2Rβγ more readily than IL2Rαβγ and this property is an inherent feature of NKTR-214 that promotes its favorable biological and therapeutic effects in murine tumor models." (PMID 28678791, 2017). "In addition, shRNA knocking out NKTR expression can significantly promote tumor cell migration and invasion, suggesting that NKTR may play an inhibitory role in tumor metastasis." (PMID 36006421, 2022). "NKTR-214 may trigger a more vigorous local immune response within the tumor microenvironment." (PMID 31484560, 2019). "Furthermore, the tumor/plasma ratio of NKTR-102 was 170 compared to 4 for irinotecan." (PMID 26463521, 2015). "In another work aiming to improve the proliferation, homing, and persistence of anti-tumor ACT cells, NKTR-214, a novel IL2Rβγ-biased cytokine, was designed to function as an alternative to conventional IL-2." (PMID 34000441, 2021). "The events that showed the most decreased PSI in the tumor were those in ANKRD36 (an uncharacterized gene with an ankyrin repeat domain), LMO7 (PDZ and the LIM domain-containing), and NKTR (facilitates natural killer cell binding to targets)." (PMID 34440489, 2021). "Overall, NKTR-214 strongly promoted proliferation and suppressed apoptosis of CD8+ Teff in tumor and spleen." (PMID 32005826, 2020). "Ki-67 expression marker analysis showed that ACT + NKTR-214 treatment resulted in an increased proliferation of T cell clusters, particularly CD8 T cells in spleen and tumor at both time points." (PMID 32005809, 2020). "In summary, we report therapeutic synergy of NKTR-214 with PD-1 and CTLA-4 CPI therapy and with vaccination in multiple tumor models and mouse strains, accompanied by dramatically increased systemic and intratumoral CD8+ T-cell responses." (PMID 32005826, 2020). "Together, these results indicate that NKTR-214 enhances CD8+ Teff responses and tumor control after anticancer vaccination." (PMID 32005826, 2020). "It was noted that by day 9 and before the second dose of NKTR-214 or IL-2, a substantial decrease in the BLI signal was observed in spleen and tumor, independently of the treatment, consistent with a q9d dosing schedule." (PMID 32005809, 2020). "Remarkably, up to 40% of intratumor lymphocytes were tumor antigen-specific at day 7 and up to 22% at day 14 in the ACT + NKTR-214 group." (PMID 32005809, 2020). "Together, these results indicate therapeutic benefit of NKTR-214 in combination with CPI therapy in multiple mouse strains and tumor models." (PMID 32005826, 2020).
tumor (continued). "In both spleen and tumor, ACT + NKTR-214 increased polyfunctionality by 1.7 and 10 fold, respectively, compared to ACT + IL-2." (PMID 32005809, 2020). "In this study, the ability of NKTR-214 to preferentially bind to IL-2Rβ over IL-2Rα induces a greater CD8+ T cell to Treg cell ratio, greater exposure to IL-2 in the tumor and a more robust anti-tumor immunity in comparison to aldesleukin." (PMID 31058083, 2019). "We hypothesized that NKTR-214/NKTR-262 immunotherapy would promote synergistic activation of immunostimulatory innate immune responses along with systemic adaptive anti-tumor responses to significantly improve abscopal responses, tumor regression, and overall survival." (PMID 30400835, 2018). "Syngeneic mouse tumor models with diverse histologies (CT26, EMT6, 4T1) were assessed for NKTR-262 and NKTR-214 combination treatment efficacy and immune system activation." (PMID 30400835, 2018). "NKTR-262 and NKTR-214 combination effect on T cell clonality and TIL infiltration were assessed by Adaptive ImmunoSEQ platform in the CT26 tumor model." (PMID 30400835, 2018). "The motivation for understanding this phenomenon stems from our previous observation that NKTR-214 significantly mobilizes and increases the number of CD8 T cells in the tumor microenvironment, while Treg numbers remain unchanged or decline." (PMID 28678791, 2017). "In the NB (SK-N-FI)-xenografted mice, NKTR-255 alone did not have a significant effect on NB xenograft tumor growth or animal survival." (PMID 39554906, 2024). "We hypothesized that immunotherapy with anti-CTLA-4 and bempegaldesleukin (BEMPEG; NKTR-214), a CD122-preferential IL2 pathway agonist, after primary tumor RT or resection would reduce metastases in a syngeneic murine NSCLC model." (PMID 33937052, 2021). "NKTR-214 selectively expands intratumoral Teff over Tregs, and induces Teff-derived cytokine release that drives selective depletion of Tregs in the tumor tissue but not the periphery." (PMID 32005826, 2020). "Interestingly, dendritic cell populations represented an important fraction of the tumor immune cells in both ACT + IL-2 and ACT + NKTR-214-treated mice at an early time point (30.3% and 18.2%, respectively)." (PMID 32005809, 2020). "Mechanistically, NKTR-214 provides sustained signaling through the IL-2 receptor pathway (IL-2Rβγ) to preferentially activate and expand effector CD8+ T and NK cells and RT modulates the tumor microenvironment (TME) to induce antigen-release." (PMID 30400835, 2018). "One tumor harbored NKTR-PLAG1, where PLAG1 was fused with intron 10 of the inverted NKTR gene." (PMID 29084941, 2017). "Since NKTR-214 alone has little effect, it has been speculated that NKTR-214 and immune checkpoint inhibitors (anti-PD-1, anti-CTLA-4) have a synergistic effect in resisting tumor, and this has been strongly supported in some preclinical and clinical experiments." (PMID 36936961, 2023). "The observation that NKTR-214 treatment mediated selective Treg depletion of intratumoral but not of peripheral Tregs suggests that in patients with cancer, NKTR-214-containing regimens could increase tumor control without exacerbating systemic inflammation." (PMID 32005826, 2020). "NKTR-214 and aldesleukin monotherapy did not suppress tumor growth." (PMID 32005826, 2020). "NKTR-214 as a monotherapy and in combination with anti-PD-1 antibodies or Toll-like receptors (TLR) agonists, is currently being evaluated in an outpatient setting in several clinical trials, showing early evidence of efficacy in multiple tumor types along with a favorable outpatient dosing." (PMID 32005809, 2020). "NKTR-214 is an investigational, first-in-class, CD122 preferential agonist that functions as a pegylated recombinant interleukin-2 (IL-2) with cellular effects in activation of CD8+ T and natural killer (NK) cells without unwanted expansion of T regulatory (Treg) cells in the tumor microenvironment." (PMID 31484560, 2019).
tumor (continued). "NKTR-214 synergizes with checkpoint blockade as well as with vaccination to improve the survival, proliferation and tumor infiltration of effector CD8+ T cells while promoting selective intratumoral depletion of Tregs to establish effective anti-tumor immunity." (PMID 30400822, 2018). "Relative to NKTR-214 alone, NKTR-214 and anti-PD-1 combination resulted in somewhat lower levels of CD8+ T cells in the blood, which could be due to enhanced transitioning of CD8+ T cells from the blood into the tumor mass as observed in this combination treatment group." (PMID 32005826, 2020). "In contrast, NKTR-214 drastically reduced the proliferation and enhanced the apoptosis of CD4+ Tregs in tumor tissue, but not in spleen." (PMID 32005826, 2020). "Results showed that the exon skipping events of FIP1L1, NKTR, and ADD3, but not ATP5F1C, occurred in most tumor tissues highly expressing CDYL2a compared to matched normal breast tissues." (PMID 32373210, 2020). "NKTR-214 shows superior anti-tumor activity over native IL-2 and systemically expands anti-tumor CD8+ T cells while inducing Treg depletion in tumor tissue but not in the periphery." (PMID 32005826, 2020).
cancer (11 papers, 2020 to 2024). A tumor composed of atypical neoplastic, often pleomorphic cells that invade other tissues. "Several current products include ALT-803 ALT-803, P22339, chimeric IL-15 apolipoprotein A-I, or NKTR-255, illustrating the promise of IL-15 in cancer therapy." (PMID 36467072, 2022). "NKTR-262 is another TLR7/8 agonist being evaluated in the context of intratumoral administration in advanced cancers in combination with the CD122 agonist NKTR-214." (PMID 34058283, 2021). "To understand the activity and mechanism of action of NKTR-214 in T-cell-based immunotherapy of cancer, we studied its use in preclinical models of PD-1 and CTLA-4 CPI therapy and in antigen-specific vaccination as well as in patient samples." (PMID 32005826, 2020). "Together, these results shed light on the mechanism of action of NKTR-214 and inform its clinical application in combination with immune-based therapies for patients with cancer." (PMID 32005826, 2020). "In addition, the exon 6 of Natural Killer T-cell Receptor (NKTR), another crucial cancer gene, was excluded in both cellular systems expressing HBZ." (PMID 35979358, 2022). "Compared to rhIL-15, NKTR-255 induced a 2.5- and 2.0-fold increase in NK and CD8+ T cells, respectively, in multiple cancer models." (PMID 36936961, 2023). "Functionally, NKTR-255 induces the proliferation and activation of NK and CD8+ T cells, increases the CD8+:regulatory T cell ratio, increases the accumulation and persistence of anti-CD19 CAR T cells in the bone marrow, and synergizes with monoclonal antibodies to enhance ADCC in cancer models." (PMID 39554906, 2024).
NKTR also shares sentences with these, for which no sentence is quoted: schizophrenia (2 papers); colorectal cancer (1); Ewing sarcoma (1); Fanconi anemia (1); heart transplant (1); lung carcinoma (1); meningioma (1); metabolic disorders (1); metastatic cancers (1); neuroblastoma (1); neurological diseases (1); theileriasis (1).